METTL14 (methyltransferase 14, N6-adenosine-methyltransferase non-catalytic subunit)
Diseases named in the same sentence as METTL14 in open-access papers (continued):
Sharing a sentence is not in itself a finding about the gene and the disease.
colorectal cancer (95 papers, 2020 to 2026). A primary or metastatic malignant neoplasm that affects the colon or rectum. "For instance, METTL14, which is underexpressed in colorectal cancer (CRC) and linked to a poor prognosis, reduces m6A levels on XIST and enhances YTHDF2-mediated XIST expression, thereby inhibiting tumor cell growth." (PMID 40271153, 2025). "Low expression of METTL14 has been linked to an unfavorable prognosis among colorectal cancer patients." (PMID 38171932, 2023). "The loss of METTL3 or METTL14 was shown to enhance the sensitivity of colorectal cancer and melanoma to anti-PD-1 treatment." (PMID 34858499, 2021). "Loss of METTL14 in human colorectal cancers correlates with high levels of XIST and poor patient survival." (PMID 33564819, 2021). "For example, loss of METTL3 and METTL14 expression increases the response to anti-PD-1 treatment in colorectal cancer with low mutational burden." (PMID 34616742, 2021). "Furthermore, MRTX1133 suppresses progression of KRAS G12D-mutated colorectal cancer by inducing ferroptosis via the METTL14/LINC02159/FOXC2 axis." (PMID 40746552, 2025). "The depletion of METTL14 might cause improvement of proliferative, invasive and migrative ability in colorectal cancer cells." (PMID 36875073, 2023). "METTL14 could regulate the m6A level of XIST, and the loss of METTL14 is related to poor prognosis of patients with colorectal cancer." (PMID 36387210, 2022). "The loss of METTL14 is related to the poor prognosis of colorectal cancer patients." (PMID 33552994, 2020). "Similar to other tumors, the regulation of m6A modifications in colorectal cancer is equally diverse and complex, and almost all m6A modifiers except METTL14, ZC3H13, METTL3, FTO, ALKBH5, and YTHDF2 promote colorectal carcinogenesis." (PMID 39967906, 2025). "For example, METTL14-mediated m6A on the SOX4 transcript in colorectal cancer inhibits SOX4 expression and metastasis; low METTL14 permits SOX4 protein upregulation and is associated with metastatic relapse." (PMID 41301491, 2025). "METTL14 reportedly curbs the metastasis of colorectal cancer cells by inhibiting the m6A modification of SRY-box transcription factor 4 (SOX4) mRNA, a mechanism reliant on the YTHDF2-mediated mRNA degradation pathway." (PMID 40746896, 2025). "In contrast, METTL14, another m6A writer, is downregulated in colorectal cancer (CRC), and its decreased expression promotes tumor spread." (PMID 40271153, 2025). "Knockdown of METTL14 in macrophages promotes tumor development in colorectal cancer, and knockdown of miR-126, the downstream target gene of METTL14, can also promote tumor metastasis in metastatic liver cancer." (PMID 40830264, 2025). "The evidence accumulated in recent years indicates that METTL14 inhibits the malignant progression of various cancer cells, such as colorectal cancer, liver cancer and renal cell carcinoma." (PMID 39827141, 2025). "For example, in colorectal cancer, METTL14 inhibits the proliferation, metastasis and invasion of tumor cells either by enhancing the expression of KLF4 in IGF2BP2-m6A manner, or by inhibiting YTHDF2-mediated SOX472, or by suppressing XIST." (PMID 40734692, 2025). "Clinically, METTL14 expression inversely correlates with CD8+ T-cell dysfunction in colorectal cancer." (PMID 41164187, 2025). "lingling Wang demonstrated that depletion of the methyltransferases Mettl3 and Mettl14 enhanced response to anti-PD-1 treatment in colorectal cancer and melanoma." (PMID 38030537, 2024). "As the writer of m6A, METTL14 served as an antitumor factor of colorectal cancer to affect patient prognosis." (PMID 36875073, 2023).
colorectal cancer (continued). "In this study, we found that m6A methyltransferase METTL14 was downregulated in colorectal cancer (CRC) and negatively correlated with the poor prognosis of CRC patients." (PMID 37283789, 2023). "In colorectal cancer, METTL14 was expressed lowly in cancer tissue compared with normal tissue, and METTL14 depletion was observed in patients with shorter survival times." (PMID 36875073, 2023). "They found the upregulation of more m6A‐associated genes in tumour tissues than in normal tissues, as well as the downregulation of ALKBH5, YTHDF3 and METTL14 in colorectal cancer (CRC)." (PMID 34647424, 2022). "METTL14 expression was found to be decreased in colorectal cancer patients, and Mettl14 knockdown in vitro resulted in decreased m6A deposition on downstream target Xist, a long non-coding RNA (lncRNA) that has been found to promote proliferation." (PMID 35350378, 2022). "In colorectal cancer and melanoma, loss of METTL3 and METTL14 enhanced the sensitivity to anti-PD-1 treatment." (PMID 35806168, 2022). "For instance, METTL14 inhibits colorectal cancer progression via regulating m6A-dependent primary miR-375 processing." (PMID 36288387, 2022). "This was also confirmed in another study in which the researcher found that the suppression of METTL14 can enhance the progression and metastasis of colorectal cancer." (PMID 35614935, 2022). "Previous research has identified METTL3 and METTL14 are m6A methylation writers on mRNAs, which regulate the growth and metastasis of renal cancer, colorectal cancer, pancreatic cancer, and other cancers." (PMID 36311770, 2022). "A recent study found that in colorectal cancer patients’ tumor tissue, the expression of METTL14 was negatively correlated with CD8+ T cell infiltration." (PMID 35614935, 2022). "In previous study, METTL14 has been discovered to play a role as a tumor suppressor in various cancers, such as colorectal cancer and kidney renal clear cell carcinoma." (PMID 36288387, 2022). "METTL14 suppressed colorectal cancer growth and metastasis by downregulating oncogenic long non-coding RNA XIST in the METTL14-YTHDF2-lncRNA regulatory axis." (PMID 35707365, 2022). "The higher the expression of METTL14, the longer the overall survival of the patients, and overexpression of METTL14 can suppress the metastasis and progression of colorectal cancer." (PMID 35614935, 2022). "The latest study ascertained that reduced m6A modification by knocking out methyltransferase genes, Mettl3 and Mettl14, enhanced response to PD-1 inhibitors in murine colorectal carcinoma cell line CT26." (PMID 35382776, 2022). "Further functional experiments demonstrated that METTL14 inhibited the progression of colorectal cancer by regulating the production process of m6A-dependent precursor miR-375." (PMID 34863142, 2021). "The knockdown of METTL14 markedly augmented the proliferative and invasive abilities of colorectal cancer cells." (PMID 34858499, 2021). "For example, the m6A “writer” METTL14 was reported to inhibit the proliferation and metastasis of colorectal cancer through the downregulation of the oncogenic XIST lncRNA." (PMID 34268304, 2021). "Intriguingly, the efficacy of anti‐PD‐1 is considerably augmented by simultaneous depletion of METTL3 and METTL14 in both colorectal cancer and melanoma." (PMID 34586737, 2021). "It was reported that the downregulation of METTL14 is related to poor prognosis in patients with colorectal cancer (CRC), and the knockdown of METTL14 promotes the proliferation and invasion of CRC cells." (PMID 33403026, 2021). "In colorectal cancers with low mutational burden, which are resistant to immunotherapy, depletion of METTL3 and METTL14 increases the expression of CD8+ T cells and the secretion of IFN-γ via the m6A reader YTHDF2." (PMID 34616742, 2021).
colorectal cancer (continued). "Further, the simultaneous suppression of METTL3 and METTL14 has also been demonstrated to augment the efficacy of anti‐PD‐1 therapy in colorectal cancer and melanoma, owing to the higher infiltration of CD8+ T cells and massive cytokine release in the TIME." (PMID 34586737, 2021). "METTL14 also had been reported as a suppressor for tumor metastasis in colorectal cancer, hinting towards METTL14 being valuable therapeutic target for colorectal cancer." (PMID 34476213, 2021). "The expression of METTL14 was down-regulated in colorectal cancer, which indicated a poor prognosis of patients, and promoted the proliferation and invasion of tumor cells by inhibiting the degradation of the oncogene XIST." (PMID 33363011, 2020). "Knockdown of METTL14 promotes proliferation and invasion of colorectal cancer cells in vitro and enhanced tumorigenicity and metastasis in vivo." (PMID 33372610, 2020). "Functionally, METTL14 knockdown leads to enhanced colorectal cancer cell growth and invasion in vitro and tumor growth and metastasis in vivo." (PMID 33372610, 2020). "In total, we highlight the important role of METTL14 and m6A in colorectal cancer and provide a promising marker for predicting prognosis of CRC." (PMID 32111213, 2020). "METTL14 expression is significant decreased in colorectal cancer and its lower expression is correlated with poor overall survival of patients." (PMID 33372610, 2020). "For example, METTL14 which suppresses colorectal cancer progression via regulating m6A-dependent miR-375/yes-associated protein 1 (YAP1) pathway, is downregulated in colorectal cancer tissues and cell lines." (PMID 32754191, 2020). "METTL14 may inhibit the malignant process of colorectal cancer via PI3K/AKT pathway and epithelial‒mesenchymal transition (EMT) induced by SRY-related high-mobility-group box 4 (SOX4)." (PMID 40986143, 2025). "Furthermore, METTL14 can impede the migration and invasion of colorectal cancer cells by regulating the demethylation of H3K4me3." (PMID 40746896, 2025). "For instance, METTL14 may promote CD8+ T-cell dysfunction in colorectal cancer through stabilization of Ebi3 mRNA, yet enhance T-cell activation in other contexts by facilitating PDCD1 mRNA degradation." (PMID 41164187, 2025). "Similarly, in pMMR-MSI-L colorectal cancer, METTL14 promotes YTHDF2-dependent degradation of Stat1/Irf1 mRNA, dampening IFN-γ–Stat1–Irf1 signaling and limiting CD8+ T-cell activity, which restricts PD-1 immunotherapy response." (PMID 41164187, 2025). "It has also been shown that METTL14 deletion in tumor-associated macrophages increases EBI3 and further cross-talks with T cells and leads to its differentiation/dysfunction, which promotes the colorectal cancer progression." (PMID 40734692, 2025). "In addition, METTL14 is significantly downregulated in colorectal cancer and inhibits the malignant process of colorectal cancer through the SOX4-mediated EMT process and PI3K/Akt signaling." (PMID 38725005, 2024). "Moreover, some studies reported that METTL14 represses colorectal cancer (CRC) development via the PI3K/Akt signaling, upregulated by brain-derived neurotrophic factor (BDNF), which revealed similar evidence with our GO results." (PMID 38453794, 2024). "For instance, METTL14 regulates the immune response to anti-PD-1 treatment in colorectal cancer." (PMID 38725005, 2024). "Furthermore, experiments involving the knockdown of METTL14 have revealed a significant enhancement in the proliferative and invasive capabilities of colorectal cancer cells." (PMID 38171932, 2023). "For example, the depletion of METTL3 and METTL14 could significantly increase the efficacy of anti-PD-1 therapy against colorectal cancer and melanoma." (PMID 36058919, 2022).
colorectal cancer (continued). "In contrast, another m6A writer protein, METTL14, expressed at a low level in colorectal cancer." (PMID 35614935, 2022). "On the contrary, as an essential component of m6A writer, METTL14 has been shown to suppress proliferation and metastasis of colorectal cancer by downregulating oncogenic lncRNA XIST, suggesting the regulatory network of m6A and lncRNA in tumor pathophysiology was extremely complicated." (PMID 35615374, 2022). "The role of m6A methyltransferases in tumors has been partially reported; for example, METTL3 upregulation promotes the malignant progression of HCC by inhibiting SOCS2 expression through an m6A-dependent mechanism, and METTL14 inhibits proliferation and metastasis in colorectal cancer." (PMID 35494016, 2022). "Interestingly, the YTHDF2-dependent pathway relied on by METTL14-related regulation has been discovered previously in colorectal cancer." (PMID 36288387, 2022). "Furthermore, in colorectal cancer, METTL14 inhibited migration and metastasis through m6A/YTHDF2-mediated mRNA degradation of the epithelial-to-mesenchymal transition (EMT)-promoting transcription factor Sox4." (PMID 35350378, 2022). "Interestingly, METTL14 (m6A writer) was reported to exhibit decreased levels in colorectal cancer and to attenuate colorectal cancer cell invasion and proliferation by suppressing m6A modification." (PMID 35864471, 2022). "Other studies showed that ALKBH5 could promote the metastasis and invasion of gastric cancer by demethylating the expression of lncRNA NEAT1 and that METTL14 acts as a prognostic biomarker in colorectal cancer by downregulating oncogenic lncRNA XIST." (PMID 35309906, 2022). "Oncogenic lncRNA XIST is inhibited by METTL14 (writer) in colorectal cancer." (PMID 34238292, 2021). "Similarly, METTL14 inhibited colorectal cancer cell growth and metastasis by regulating its downstream target miR-375, which is a well-known tumor suppressor miRNA, revealing the role of METTL14-dependent m6A methylation in cancer." (PMID 32709063, 2020). "Previous studies showed that METTL14 could inhibits colorectal cancer metastasis and proliferation." (PMID 37283789, 2023). "According to the TCGA database and GSE41657, METTL14 was expressed at low levels in adenoma and further decreased in colorectal carcinoma, exhibiting synchrony with CRC progression." (PMID 36810285, 2023). "IGF2BP3 functions as an m6A reader to stabilize and enhance translation of EGFR mRNA through collaboration with METTL14, thereby activating EGFR signaling and conferring therapeutic resistance to cetuximab in colorectal cancer." (PMID 40986143, 2025). "m6A in LncRNA NEAT1 was shown to exhibit oncogenic function in prostate cancer progression, METTL14-induced m6A process suppressed XIST expression, and suppresses proliferation and metastasis of colorectal cancer." (PMID 37773181, 2023). "In colorectal cancer, the reduction of METTL3 or METTL14 rises cytotoxic tumor-infiltrating CD8+ T cells and stimulates the recruitment of CD4+ and CD8+ effector T cells that suppress tumor growth." (PMID 37236993, 2023). "For example, 3-deazaadenosine inhibits METTL3/METTL14, CA4 (carbonic anhydrase member) induces WTAP degradation and suppresses colorectal cancer proliferation, and R-2-hydroxyglutarate (R-2HG) delays leukemia progression via inhibition of FTO." (PMID 35794625, 2022). "Methyltransferase-like 14 (METTL14) can suppress the growth and metastasis of colorectal cancer (CRC) via repressing X inactive specific transcript (XIST)." (PMID 35156522, 2022). "In colorectal cancer and melanoma, simultaneous depletion of METTL3 and METTL14 induces mass production of cytokines, including IFN‐γ, CXCL9, and CXCL10." (PMID 34586737, 2021). "To verify the impact of METTL14 on immune infiltration, we cultured HCT116 cells, a human colorectal cancer cell line, and FHC cells, a human normal intestinal epithelial cell line, and conducted Arraystar Human m6A-mRNA Epitranscriptomic microarray analysis." (PMID 34221955, 2021).
colorectal cancer (continued). "For instance, inhibition of METTL14 promotes the proliferation and invasion of GC cells by activating Wnt pathway, downregulation of METTL3 promotes metastasis of colorectal cancer cells through MAPK pathway." (PMID 34702266, 2021). "It’s worth to investigate the targets of ZEB1 regulating by cooperation of METTL14, YHTDF2, ARRDC4, TCF4 and HuR leads to elevation of invasiveness and migration of colorectal cancer cells in the future study." (PMID 34916487, 2021). "To investigate the potential role of m6A in colorectal cancer, we first detected the mRNA levels of major m6A methyltransferase including METTL3 and METTL14 in 37 CRC and paired normal samples." (PMID 32111213, 2020). "XIST mRNA is recognized by the m6A reading protein YTHDF2 which are further brought to be methylated by METTL14 through m6A, leading to XIST degradation, and thereby inhibits the tumorigenesis and metastasis of colorectal cancer cells." (PMID 33552994, 2020). "Consistently, clinical colorectal cancer samples show a negative correlation between METTL14 expression/m6A levels and T-cell dysfunction." (PMID 41164187, 2025). "Besides, ALKBH5, FTO, METTL3, METTL14, METTL16 and WTAP were detected in a section of colorectal cancer tissue." (PMID 39039912, 2024). "Besides being a well-known m6A writer, ALKBH5 also collaborates with METTL14/IGF2BPs to suppress tumor cell glycolysis by negatively regulating the JMJD8/PKM2 signaling axis, thereby slowing down colorectal cancer progression." (PMID 38856795, 2024). "METTL14 regulates the expression of miR-375 through DGCR8, and then inhibits the growth of cancer cells by targeting downstream YAP1 pathway, and also inhibits the invasion and migration of colorectal cancer cells." (PMID 35022030, 2022). "For example, the expression of M6A “writer” protein methyltransferase-like 14 (METTL14) is downregulated in colorectal cancer, and it has been found that XIST is downregulated by METTL14 in a YTHDF2-dependent way, which is responsible for inhibiting the growth of colorectal cancer." (PMID 36035993, 2022). "METTL14 knockout reduces the m6A level of downstream XIST, which can’t be recognized by YTHDF2 and inhibits its degradation, promotes the expression of XIST, and promotes the progress of colorectal cancer." (PMID 35022030, 2022). "Interestingly, emerging evidence indicated an opposite regulatory role of METTL3 and METTL14 in several cancers, such as glioblastoma, HCC, and colorectal cancer (CRC)." (PMID 33159022, 2020). "In agreement with previous report, the present study also identified METTL14 as a tumor suppressor gene in CRC through down-regulating oncogenic lncRNA XIST, suggesting that m6A also represent a distinct form of epigenetic dysregulation in colorectal cancer." (PMID 32111213, 2020). "Third, our analysis only described the role of METTL3 and METTL14 in HCC, whether this hypothesis applies to other types of cancer, such as colorectal cancer and glioma, needs further investigations." (PMID 33159022, 2020). "Moreover, the deletion of METTL3 or METTL14 increases the infiltration of cytotoxic CD8+ T cells and the secretion of the cytokines IFN-γ, CXCL9, and CXCL10, thereby improving the response to anti-PD-1 therapy in colorectal cancer." (PMID 40986143, 2025). "Molecular investigations indicate that ALKBH5 collaborates with METTL14/IGF2BPs to suppress tumor cell glycolysis by negatively regulating the Jumonji domain-containing protein 8 (JMJD8)/pyruvate kinase M2 (PKM2) signaling axis, slowing down colorectal cancer progression." (PMID 38856795, 2024). "Therefore, METTL14 could participate in miR-375/YAP1 and miR-375/SP1 to mediate the inhibition of colorectal cancer progression via the manner of m6A modification." (PMID 36875073, 2023). "Interestingly, in colorectal cancer and melanoma, enhanced anti-PD-1 efficacy could be achieved by depletion of METTL3 and METTL14, potentially via increased CD8+ T-cell infiltration and tumor killing function." (PMID 35794625, 2022).